CCL2 (C-C motif chemokine ligand 2)
Diseases named in the same sentence as CCL2 in open-access papers (continued):
Sharing a sentence is not in itself a finding about the gene and the disease.
rheumatoid arthritis (193 papers, 2007 to 2025). A chronic, systemic autoimmune disorder characterized by inflammation in the synovial membranes and articular surfaces. "As a potent initiator of inflammation, MCP-1/CCL2 has been implicated in the development of numerous chronic disorders, including rheumatoid arthritis, cardiovascular diseases, and PCOS." (PMID 39766252, 2024). "The Enrichr pathway assignment analysis (KEGG 2021 Human database) additionally revealed enrichment of chemokine encoding genes (CXCL1, CXCL2, CXCL3, CXCL6, CXCL5, CXCL8, CCL2) which were aligned to several pathways like amoebiasis and rheumatoid arthritis." (PMID 35646693, 2022). "Polymorphisms concerning CCL2 are further associated with premature coronary artery disease, rheumatoid arthritis, sepsis, and lupus nephritis." (PMID 33540898, 2021). "For example, CCL2 is associated with monocyte infiltration in inflammatory diseases such as rheumatoid arthritis and different tumors associated with inflammatory responses." (PMID 28424660, 2017). "Moreover, genes associated with PPAR signaling and rheumatoid arthritis, such as Fabp4 and Ccl2, were also dysregulated, further supporting CLDN17’s role in immune homeostasis and metabolic pathways." (PMID 40332125, 2025). "For example, TNF was shown to increase CCL-2 mRNA and protein secretion in endothelial cells, and the blockage of TNF actions reduces CCL-2 levels in patients with rheumatoid arthritis." (PMID 40362499, 2025). "Studies showed that various chemokines participated in RJD pathogenesis: rheumatoid arthritis patients exhibit increased levels of plasma CCL2, CCL3, CCL4, and CXCL10 and psoriatic arthritis patients also exhibited high values of CCL2 and CXCL10." (PMID 38622714, 2024). "Under the inflammation in the body, monocytes, macrophages, B cells, endothelial cells, and many other cells can secrete CCL2, which plays important roles in rheumatoid arthritis and glomerulonephritis." (PMID 39605886, 2024). "IL-6 trans-signaling also promotes secretion of CXLC8 and CCL2 by rheumatoid arthritis synoviocytes, a cell type related to mesothelial cells." (PMID 39114667, 2024). "CCR2 and CCL2 have been extensively studied in inflammatory diseases, particularly in rheumatoid arthritis." (PMID 36109442, 2023). "Serum CCL2 level was higher in patients with AOSD than in patients with rheumatoid arthritis and healthy controls (HCs)." (PMID 37500699, 2023). "TNF-α helps produce SR-A, participating in the production of CCL-2, which is a key player in rheumatoid arthritis and can stimulate chemotaxis in mononuclear cells." (PMID 36297105, 2022). "Chronic inflammation is accompanied by elevated CCL2 levels as exemplified in hepatocellular carcinoma or rheumatoid arthritis." (PMID 33540898, 2021). "There was an unexpected dose-related CCL2 increase, resulting in worsening rheumatoid arthritis in patients treated with high doses of the Ab." (PMID 33540898, 2021). "Preclinical and clinical findings further suggest that the blockade of CCL2 is an important target in the design of potential treatments for rheumatoid arthritis-induced pain." (PMID 34769165, 2021). "CCL2 is a chemokine, which mediates monocyte chemotaxis and is involved in monocyte infiltration in inflammatory diseases such rheumatoid arthritis." (PMID 33808372, 2021). "It has further been shown that the MSCs from patients with rheumatoid arthritis display impaired function with regard to the inhibition of Th17 cell polarization, which was related to the low expression of CCL2 in MSCs." (PMID 29854745, 2018). "In an in vitro co-culture system, we show that Rev-erb agonist can suppress macrophage transcript levels of select inflammatory genes (IL6, TNFα, CCL2, and MMP9), which are involved in rheumatoid arthritis and implicated in alphavirus-induced joint pathology." (PMID 30568983, 2018).
rheumatoid arthritis (continued). "For example, CCL2 is involved in monocyte infiltration in inflammatory diseases such as rheumatoid arthritis as well as in the inflammatory response against tumours." (PMID 29682101, 2018). "A phase I clinical trial study on CCL2 antibody neutralization in rheumatoid arthritis patients showed that antibody bound CCL2 complexes were still biologically active and that CCL2 levels were increased in patients." (PMID 27283985, 2016). "CCL2 neutralizing antibodies effectively blocked rheumatoid arthritis in mouse models, yet failed in clinical trials." (PMID 27283985, 2016). "Chronic overexpression of CCL2 contributes to inflammatory diseases including rheumatoid arthritis, fibrosis and macular degeneration." (PMID 27283985, 2016). "IL-22 is highly expressed in rheumatoid arthritis (RA), in which IL-22 induces production of monocyte chemoattractant protein-1 (CCL2; also known as MCP-1) and proliferation of synovial fibroblasts and osteoclasts." (PMID 22312190, 2012). "CCR2 is normally involved in the infiltration of monocytes in inflammatory diseases such as rheumatoid arthritis and its ligands include CCL2, CCL7, and CCL8." (PMID 20976171, 2010). "CCL2 and CCL20 are chemokines implicated in rheumatoid arthritis synovitis and are produced by OA synovium in the presence of pro-inflammatory cytokines." (PMID 20799933, 2010). "Previous research has suggested that CCL2 might play an important role in several inflammatory diseases, e.g., inflammatory bowel disease, rheumatoid arthritis and asthma." (PMID 40463390, 2025). "Moreover, CCL2 has been regarded as the potential predictive factor of numerous inflammation-related diseases mainly including rheumatoid arthritis and OA." (PMID 35038982, 2022). "Our results suggest that the peripheral blockage of Sig-1R via CCL2 may be a promising approach to achieving an analgesic effect for the treatment of inflammatory pain diseases including rheumatoid arthritis." (PMID 34769165, 2021). "CCL2 (MCP-1) belongs to the C-C class of chemokines, and is a critical regulator of macrophage recruitment during wound healing, infection and chronic inflammatory diseases such as rheumatoid arthritis." (PMID 31208996, 2019). "Additionally, the CCL2/CCR2 axis is now considered an inappropriate target for rheumatoid arthritis, which would account for clinical trial failures." (PMID 28792472, 2017). "CCL2 (ENSP00000225831), as a functional chemokine that attracts monocyte and basophils, has been widely reported to participate in monocyte proliferation associated disease, such as psoriasis and rheumatoid arthritis." (PMID 28787010, 2017). "Therefore, the identification of TNF-α and CCL2 antagonists from natural sources would represent a new approach for the management of various chronic inflammatory conditions, including rheumatoid arthritis and cardiovascular diseases like arthrosclerosis." (PMID 25878716, 2015). "Accumulating evidences demonstrated that visfatin was identified as a proinflammatory adipocytokine and secreted extracellularly to upregulate inflammatory cytokines, such as TNF-α, IL-1β, IL-6 and CCL2 in rheumatoid arthritis synovial fibroblasts and monocytes in response to inflammatory stimuli." (PMID 25993304, 2015). "Significantly elevated levels of MCP-1/CCL2 were found in synovial fluids of patients with rheumatoid arthritis (RA), compared to osteoarthritis or other arthritis patients." (PMID 36768186, 2023). "An A to G single nucleotide polymorphism (SNP) in the CCL2 enhancer region (rs1024611, originally designated as –2518G or –2578G) has been associated with several chronic inflammatory conditions such as systemic lupus erythematosus (SLE) and rheumatoid arthritis." (PMID 33422029, 2021).
rheumatoid arthritis (continued). "The CCL2(MCP-1)-CCR2 axis plays a pivotal role in monocyte-macrophage trafficking to sites of inflammation and has been implicated in the pathogenesis of various disease processes such as cardiovascular disease, diabetic nephropathy, rheumatoid arthritis, and several infectious diseases." (PMID 23166687, 2012). "It was reported that the levels of CCL2 are increased in the blood, synovial fluid, and synovial tissue of patients with OA and rheumatoid arthritis (RA)." (PMID 23185512, 2012). "The DEGs which contributed to the pathway term “Rheumatoid arthritis” were CXCL8 (C-X-C Motif Chemokine Ligand 8), CTSL (Cathepsin L), CXCL2 (C-X-C Motif Chemokine Ligand 2), and CCL2 (C-C Motif Chemokine Ligand 2)." (PMID 36911677, 2023). "In this model of rheumatoid arthritis, the fibroblast secretion of IL-6, CXCL12, and CCL2 in the synovial microenvironment, as well as the expression of an IFN-γ gene signature, stimulates the macrophage-mediated inflammatory response." (PMID 36559029, 2022). "In the clinical setting, a high degree of concordance has been demonstrated between the status of oxidative stress in rheumatoid arthritis and the levels of MIP-1β/CCL4 and MCP-1/CCL-2." (PMID 36293292, 2022). "Mechanistically, these expanded inflammatory Thy1+ fibroblasts were shown to drive inflammation in rheumatoid arthritis by secreting IL6 and chemokines such as CCL2, CX3CL1, CXCL9, and CXCL12." (PMID 35085231, 2022). "CCL2/MCP-1 and CCL3/MIP-1α are substances primarily identified in patients with rheumatoid arthritis." (PMID 34199256, 2021). "This drug also has excellent therapeutic effects for tumors, coronary stent restenosis, acute pancreatitis, rheumatoid arthritis and other MCP-1/CCL2-induced inflammatory diseases 17-20." (PMID 32863944, 2020). "GA suppresses the expression of several proinflammatory mediators, such as IL-6, IL-1β, CCL2 and CCL7, in fibroblast-like synoviocytes from rheumatoid arthritis patients." (PMID 31026283, 2019). "The expression and involvement of both CCL2 and its receptor CCR2 have been established in several pathological conditions, including rheumatoid arthritis, atherosclerosis, multiple sclerosis, cancer-induced bone loss, and bacterially induced bone loss." (PMID 28424660, 2017). "In the rheumatoid arthritis arena, two inhibitors have shown promise: one is a CCR2/CCL2 inhibitor INCB3344 and the other is a monomeric variant P8A-CCL2 antagonist." (PMID 28974038, 2017). "Chemokine (C-C motif) ligand-2 (CCL2)/MCP-1 are known to be expressed in OA and rheumatoid arthritis." (PMID 25313362, 2014). "Chemokines such as IL-8, CCL2 and CCL20 are produced by OA synoviocytes, but to a lower extent than rheumatoid arthritis cells." (PMID 20799933, 2010). "Moreover, high levels of inflammatory/arthrogenic factors, including cytokines (TNF-α, IL-6, IL-7, IL-15, and BAFF) and chemokines (CCL-2, CCL-5, and CXCL-10) have been reported in the serum and/or synovia of rheumatoid arthritis patients." (PMID 38720890, 2024). "Interestingly, the five cytokines (CCL2, CCL3, CCL20, CXCL1, and IL8) that are involved in the leukocyte infiltration in the blood vessel of rheumatoid arthritis patients are also found in the xenoAMP(S)-poly(I:C) activated HDMVEC." (PMID 38306481, 2024). "TNFα, IL-1β, and hypoxia also up-regulate the expression of cytokines, including IL-6, CXCL8 (namely, IL-8), CCL2, CXCL11, CXCL12, and VEGF, as well as the expression of cytokine receptors such as TNFRSF9 in synovial fibroblasts derived from rheumatoid arthritis (RA) patients." (PMID 35967331, 2022). "Taken together, these results did not support a beneficial role of CCL2 Ab treatment in the context of rheumatoid arthritis." (PMID 33540898, 2021). "In the rheumatoid arthritis pathway, TGF-β1 induced Ccl2 and suppressed Ctsl and Mmp3." (PMID 33149203, 2020). "CCL2 and CCR2 are extensively studied in rheumatoid arthritis." (PMID 30937315, 2019).
rheumatoid arthritis (continued). "Furthermore, several genes that were annotated in studies on rheumatoid arthritis (VEGFA, TGFB2, MMP1, MMP3, IL8, CCL3L1, CTSL1, CCL2) were also significantly upregulated in the immature articular cartilage in our study." (PMID 27045355, 2016). "Considering that rheumatoid arthritis is a chronic disease, antioxidant properties allied to TNF-α and CCL2 inhibition might be beneficial for inflammation resolution." (PMID 25878716, 2015). "A selective anti-TNF-α effect is desirable for developing new antirheumatic drugs, since the administration of CCL2 monoclonal antibody to patients with rheumatoid arthritis did not ameliorate the disease and even aggravated the symptoms at higher doses." (PMID 25878716, 2015). "In the setting of rheumatoid arthritis, pro-inflammatory cytokine levels are elevated, which includes IFN-γ, TNF-α, IL-6, IL-1, GM-CSF and chemokines such as chemokine C-C motif ligand 2 (CCL2) and CCL13." (PMID 25501574, 2014). "In rheumatoid arthritis (RA), fibroblasts activated by tumor necrosis factor (TNF) produce high levels of chemokines such as IL-6, CXCL12, and CCL2, which enhance the recruitment and attraction of monocytes." (PMID 39290699, 2024). "However, in the context of rheumatoid arthritis, treatment with human anti-CCL2 monoclonal Ab does not have a benefit compared with placebo control." (PMID 33540898, 2021). "In addition, prostaglandin E2 (PGE2), CCL2 and interleukin 1 receptor antagonist (IL1RA), which are produced by MSC have shown to have an important role in the therapeutic effects of MSC on autoimmune diseases, such as rheumatoid arthritis." (PMID 28595619, 2017). "CCR2 is a chemokine receptor for monocyte chemoattractant protein-1 (MCP-1 or CCL2) and important for monocyte trafficking toward sites of inflammation, a process that is critical for autoimmune diseases like rheumatoid arthritis (RA) and CIA." (PMID 21991368, 2011). "Moreover, studies in patients with rheumatoid arthritis (RA) showed that fibroblast-like synoviocytes (FLS) constitutively express CCR2, CCR5, CXCR3,and CXCR4; in addition, stimulation with CCL2, CXCL12, CXCL9, and CXCL10 enhances FLS migration and proliferation." (PMID 28883822, 2017).
type 2 diabetes (190 papers, 2008 to 2025). "The same group reported that enarodustat also exerted renoprotective effects against metabolic disorders and associated kidney disease in obese type 2 diabetic mice by improving glucose and lipid metabolism and suppression of CCL2/MCP-1." (PMID 35281917, 2022). "Baricitinib down-regulates urine CCL2 expression with a decreased urine albumin–creatinine ratio (UACR) in type 2 diabetes patients at high risk for progressive DN in a phase 2 randomized controlled clinical trial." (PMID 32365893, 2020). "For example, a promoter polymorphism (-2518A/G) in the CCL2 gene was found to be associated with progressive kidney failure in Koreans with type 2 diabetes and TGFB1 T869C gene polymorphism showed association with nephropathy in type 2 diabetic Chinese patients." (PMID 19357773, 2009). "Pharmacological blockade of CCL2 or CCR2 have successfully entered clinical trials studying treatment of type 2 diabetes and nephropathy." (PMID 35699239, 2022). "The data obtained in the current study suggest that blockade of CCL2 is indeed able to improve hyperglycaemia in patients with type 2 diabetes." (PMID 28186566, 2017). "Power assuming α = 0.05 and relative risk of 1.4 was 62%, 83%, 85% and 79% for type 2 diabetic patients with diabetic nephropathy for IL8, CCL2, CCR5, MMP9 polymorphisms (p<0.05) among North Indian population." (PMID 19357773, 2009). "In multivariate analysis, the association between advanced fibrosis (F3-F4) and CCL2 levels remained significant (p = 0.017) after adjusting for the AST/ALT ratio and presence of type 2 diabetes, which were the only other factors independently associated with advanced fibrosis in our cohort." (PMID 35743140, 2022). "Interestingly, it has been suggested that the CCL2 expression was elevated by promoter hypomethylation in patients with Type 2 diabetes than controls." (PMID 35038982, 2022). "In the rat model of type 2 diabetes, pioglitazone significantly reduces macrophage infiltration in renal tissue along with inflammatory and fibrotic factors such as NF-κB, chemokine (C-C motif) ligand 2 (CCL2) TGF-B, PAI, and vascular endothelial growth factor (VEGF)." (PMID 32158560, 2020). "CCL2 levels were increased in urine samples of NE, type 2 diabetes, CKI, and SLE." (PMID 29682100, 2018). "The established risk biomarkers include CCL2, matrix metallopeptidases (MMPs), tyrosine kinase, podocin, connective tissue growth factor, tumor necrosis factor (TNF)-receptor-1, sclerostin, YKL-40, and NT-proCNP, which improve the explanations and prediction of eGFR decline in type 2 diabetes." (PMID 32365893, 2020). "Moreover, the expression level of CCl2 was increased in patients with systemic skeletal disease such as osteoporotic patients, and the serum level of CCL2 was greater up to 4 weeks postsurgery in patients with type 2 diabetes compared to healthy patients." (PMID 28303118, 2017). "A meta-analysis concluded that the concentration of CCL2 and CCL5 were significantly higher in type 2 diabetic patients when compared to controls." (PMID 39518420, 2024). "Correlating these data, we can assume that CCL2, CCL5, IL-6, IL-1β, and leptin can play a significant role in MDSC recruitment in the adipose tissue of patients with type 2 diabetes." (PMID 39518420, 2024). "With the exception of CCL-2 (p = 0.09), differences in TNF-α (p < 0.0001), hs-CRP (p < 0.05), IL-6 (p < 0.05) and adiponectin remained significant after excluding subjects with type 2 diabetes (n = 7) from the NASH cohort." (PMID 24962805, 2014). "However, in another study of 31 patients with type 2 diabetes and high albuminuria treated with the SGLT2 inhibitor dapagliflozin, we observed a reduction in urinary CCL2 levels." (PMID 31001673, 2019). "Linagliptin, a DPP-4 inhibitor, reduces CCL2, CCL22, and IL-12 in type 2 diabetes patients with or without DN compared with the placebo group, suggesting its anti-inflammatory abilities in type 2 DM." (PMID 32365893, 2020).